PSMB6 (proteasome 20S subunit beta 6)
Description:
Component of the 20S core proteasome complex involved in the proteolytic degradation of most intracellular proteins. This complex plays numerous essential roles within the cell by associating with different regulatory particles. Associated with two 19S regulatory particles, forms the 26S proteasome and thus participates in the ATP-dependent degradation of ubiquitinated proteins. The 26S proteasome plays a key role in the maintenance of protein homeostasis by removing misfolded or damaged proteins that could impair cellular functions, and by removing proteins whose functions are no longer required. Associated with the PA200 or PA28, the 20S proteasome mediates ubiquitin-independent protein degradation. This type of proteolysis is required in several pathways including spermatogenesis (20S-PA200 complex) or generation of a subset of MHC class I-presented antigenic peptides (20S-PA28 complex). Within the 20S core complex, PSMB6 displays a peptidylglutamyl-hydrolizing activity also termed postacidic or caspase-like activity, meaning that the peptides bond hydrolysis occurs directly after acidic residues.
Synonyms: LMPY; Y; DELTA
Tractability: Small molecule: an approved drug acts on it; a structure with a bound ligand is known; a high-quality ligand is known; it belongs to a druggable protein family. PROTAC: ubiquitination databases record sites on it; its protein half-life has been measured; a small molecule that binds it is known.
Target class: Threonine protease; Protease; Threonine protease T1A subfamily; Threonine protease PBT clan; Enzyme
Gene: Protein-coding gene on chromosome 17 (4,796,144 to 4,798,503, forward strand). Ensembl gene ENSG00000142507.
Subcellular location: Cytoplasm; Nucleus
Subcellular location (Human Protein Atlas): Cytosol; Nucleoplasm; Mitochondria
Pathways (Reactome):
Immune System: AMPK-induced ERAD and lysosome mediated degradation of PD-L1(CD274); Activation of NF-kappaB in B cells; Antigen processing: Ub, ATP-independent proteasomal degradation; Antigen processing: Ubiquitination & Proteasome degradation; CLEC7A (Dectin-1) signaling; Cross-presentation of soluble exogenous antigens (endosomes); Dectin-1 mediated noncanonical NF-kB signaling; Downstream TCR signaling; ER-Phagosome pathway; FCERI mediated NF-kB activation; GSK3B-mediated proteasomal degradation of PD-L1(CD274); Interleukin-1 signaling; NIK-->noncanonical NF-kB signaling; SPOP-mediated proteasomal degradation of PD-L1(CD274); TNFR2 non-canonical NF-kB pathway
Cell Cycle: APC/C:Cdc20 mediated degradation of Securin; APC/C:Cdh1 mediated degradation of Cdc20 and other APC/C:Cdh1 targeted proteins in late mitosis/early G1; Autodegradation of Cdh1 by Cdh1:APC/C; Autodegradation of the E3 ubiquitin ligase COP1; Cdc20:Phospho-APC/C mediated degradation of Cyclin A; FBXL7 down-regulates AURKA during mitotic entry and in early mitosis; G2/M Checkpoints; SCF(Skp2)-mediated degradation of p27/p21; SCF-beta-TrCP mediated degradation of Emi1; Separation of Sister Chromatids; The role of GTSE1 in G2/M progression after G2 checkpoint; Ubiquitin-Mediated Degradation of Phosphorylated Cdc25A; Ubiquitin-dependent degradation of Cyclin D
Signal Transduction: Asymmetric localization of PCP proteins; Degradation of AXIN; Degradation of DVL; Degradation of GLI1 by the proteasome; Degradation of GLI2 by the proteasome; Degradation of beta-catenin by the destruction complex; GLI3 is processed to GLI3R by the proteasome; Hedgehog 'on' state; Hedgehog ligand biogenesis; MAPK6/MAPK4 signaling; Negative regulation of NOTCH4 signaling; Regulation of PTEN stability and activity
and 28 more pathways
Gene Ontology:
Molecular function: cadherin binding; protein binding; threonine-type endopeptidase activity; endopeptidase activity
Biological process: proteasomal protein catabolic process; proteasome-mediated ubiquitin-dependent protein catabolic process; regulation of proteasomal protein catabolic process; response to oxidative stress; apoptotic process; cellular response to type I interferon; DNA damage response; DNA repair; flagellated sperm motility; meiotic cell cycle; proteasomal ubiquitin-independent protein catabolic process; regulation of G1/S transition of mitotic cell cycle; spermatogenesis; protein catabolic process
Cellular component: cytoplasm; cytosol; extracellular exosome; nucleoplasm; nucleus; proteasome complex; proteasome core complex; proteasome core complex, beta-subunit complex; proteasome storage granule; spermatoproteasome complex; synaptic vesicle
Genetic constraint (gnomAD): Loss-of-function variants: 11 observed, 25.27 expected, observed/expected ratio (o/e) 0.44, 90% interval 0.27 to 0.72. The upper end of that interval is the gene's LOEUF score, 0.72, which puts it in group 2 of 6, group 1 being the genes least tolerant of losing a copy. Missense variants: 240 observed, 293.72 expected, observed/expected ratio (o/e) 0.82, 90% interval 0.74 to 0.91. Synonymous variants: 114 observed, 108.09 expected, observed/expected ratio (o/e) 1.05, 90% interval 0.9 to 1.23.
Homologues: Orthologues: chimpanzee PSMB6 (99% identical), macaque PSMB6 (98% identical), dog PSMB6 (96% identical), guinea pig PSMB6 (94% identical), mouse Psmb6 (94% identical), rat Psmb6 (93% identical), rat Psmb6l1 (93% identical), rabbit PSMB6 (86% identical), tropical clawed frog psmb6 (78% identical), zebrafish psmb6 (73% identical), Drosophila melanogaster Prosbeta1 (51% identical), Caenorhabditis elegans pbs-1 (42% identical). Paralogues in human: PSMB9 (54% identical), PSMB7 (30% identical), PSMB11 (29% identical), PSMB8 (29% identical), PSMB5 (28% identical), PSMB10 (27% identical), PSMB4 (22% identical), PSMA5 (19% identical), PSMB1 (19% identical), PSMA4 (18% identical), PSMB3 (18% identical), PSMA8 (17% identical), and 6 more.